INS (insulin)
Diseases named in the same sentence as INS in open-access papers (continued):
Sharing a sentence is not in itself a finding about the gene and the disease.
Insulin resistance (continued). "The inactivation of IR in the ARC of the hypothalamus with antisense oligonucleotides led to insulin resistance in the liver and, consequently, to a weakening of the ability of insulin to suppress the peripheral glucose production by hepatocytes, inducing the moderate hyperglycemia and dyslipidemia." (PMID 28031898, 2015). "Weight, BMI, Waist Circumference (WC), Waist-to-Height Ratio (WHtR), fasting and 2-hour glucose and insulin, homeostasis model assessment of Insulin Resistance (HOMA-IR), HbA1c, total and free testosterone, and Ferriman-Gallwey scores were measured before and after the 8-week intervention." (PMID 26225266, 2015). "This increase may be related to increased insulin resistance and higher demand for insulin in T2D subjects." (PMID 26077345, 2015). "This is in line with the observation that metformin reduces insulin resistance, suppresses tumour formation, and inhibits cell growth, while insulin may promote carcinogenesis." (PMID 26074956, 2015). "Non-diabetic CRS rats showed significant (P<0.01, P<0.001, P<0.001) reduction in insulin response at 60, 90 and 120 min point measure respectively while diabetic CRS rats showed significant (P<0.05) reduction in insulin response at 120 min point measure, denoting the development insulin resistance." (PMID 25826421, 2015). "Defects in fatty acid oxidation may cause the accrual of fatty acyl CoAs and diacylglycerol in the skeletal muscle of obese subjects, resulting in inhibition of insulin-mediated glucose uptake and insulin resistance." (PMID 25784953, 2015). "Of note, when insulin resistance index (HOMA-IR) as well as serum insulin, leptin and adiponectin levels were compared in EC patients, it was found that SO and MHO groups can be most effectively distinguished by HOMA-IR value and the ratio of leptin/adiponectin in serum." (PMID 28031919, 2015). "On the other hand, in this study, the patients with higher glucose concentrations presented elevated insulin values, insulin resistance defined by HOMA-IR, significantly higher hsCRP and beta2M serum concentrations than the patients with lower glucose concentrations." (PMID 29371512, 2015). "Deleterious mutations in this gene impair insulin resistance and can cause lack of response to insulin." (PMID 26448950, 2015). "The proposed mechanism for this deterioration in glycemic control was termed insulin resistance of puberty, which is believed to be driven by the significantly elevated levels of anti-insulin hormones namely growth hormone and sex steroids, during the period of active pubertal maturation." (PMID 26367281, 2015). "Hence, the two major pathological features of type 2 diabetes including peripheral insulin resistance and defective insulin secretion are both affected by ER stress and UPR." (PMID 26613076, 2015). "Importantly, wild type but not PDZ-RhoGEF KO mice, developed glucose intolerance and insulin resistance, as well as impaired insulin-dependent glucose transport in the soleus and EDL." (PMID 26512886, 2015). "In addition, insulin resistance and increased plasma levels of glucose, insulin, and triglycerides resemble human NASH (BC+)." (PMID 26064924, 2015). "We next investigated whether insulin resistance in the peripheral tissues affected the phosphorylation/dephosphorylation of srGAP3 in the brains of mice subjected to intraperitoneal insulin injection after a fast." (PMID 26499801, 2015). "In the elderly, cerebral insulin resistance might be partially attributed to an impaired transport of insulin into the central nervous system." (PMID 25965336, 2015). "It is still unclear, however, whether insulin concentrations or insulin resistance play a role in memory function in the normoglycemic population." (PMID 25798199, 2015).
Insulin resistance (continued). "Because a diet high in rapidly absorbed carbohydrates and low in cereal fiber augments postprandial glycemia and insulin secretion it may contribute to glucotoxicity as well as increased insulin demand and eventually the development of insulin resistance." (PMID 25723719, 2015). "Although the exact mechanisms linking insulin resistance to these conditions are unknown, experimental data indicate that elevated circulating insulin within the hyperinsulinemic range is a fundamental component of these links." (PMID 26305095, 2015). "Strategies that improve skeletal muscle metabolic function and insulin sensitivity could therefore have a major impact on the obesity induced development of insulin resistance and diabetes and reduce health care costs and improve quality of life." (PMID 26610527, 2015). "Indeed, NDGA treatment significantly upregulated hepatic insulin signaling, as evidenced by an improvement in insulin resistance." (PMID 26394137, 2015). "A hypothesis about the association between insulin resistance and benign prostatic hyperplasia is based on the mechanism where the increased levels of insulin result in insulin resistance and thus increased levels of insulin-like growth factors (IGF 1)." (PMID 25809513, 2015). "To determine insulin resistance, we measured fasting insulin and glucose levels solely at 21 weeks." (PMID 26098416, 2015). "For the insulin resistance threshold used, insulin was far more relevant than glucose in discriminating insulin resistance, carrying almost all the necessary information (area under curve 0.995) to discriminate insulin resistance with high sensitivity and specificity." (PMID 26241903, 2015). "Obesity has been stated to be the most important cause in the development of insulin resistance and it has been demonstrated that the critical determinant of insulin sensitivity is not the degree of obesity per se but the distribution of fat partitioning." (PMID 26704130, 2015). "Obesity not only causes insulin resistance, but also leads to pancreatic β-cell damage which manifests as the impaired insulin secretion in response to glucose and nonfuel stimuli rather than reduced β-cell mass." (PMID 26445593, 2015). "Similarly, IL-10 secreted by M2 macrophages enhances insulin signaling in the liver and skeletal muscle and protects against obesity-induced insulin resistance." (PMID 26197341, 2015). "Parameters derived from the OGTT included measures of glycemia (fasted glucose and AUCglucose); measures of insulin resistance (fasted insulin, AUCinsulin, and HOMA index of insulin resistance); and a measure of pancreatic Beta cell secretory capacity (insulinogenic index)." (PMID 26074813, 2015). "Obesity might increase the expression of some inflammatory cytokines and activate several signaling pathways, both of which are involved in the pathogenesis of insulin resistance by interfering with insulin signaling and action." (PMID 26136779, 2015). "Moreover, CD36 expression is increased and positively correlates with plasma insulin levels, insulin resistance, and the degree of steatosis in NAFLD patients." (PMID 26085100, 2015). "Fasting glucose and insulin were used to derive the HOMA-index of insulin resistance (HOMA-IR)." (PMID 26437649, 2015). "However, it is worth of note that there is a strong correlation between corticosteroid receptors and insulin AUC, BMI and, to a minor extent, insulin levels and insulin resistance in the pre-treatment period, when the insulin secretion was increased." (PMID 26269722, 2015). "Calculation of the HOMA index of degree of insulin resistance (HOMA-IR) demonstrated decreased insulin sensitivity in transgenic DNHNF-1αbmf+/+ mice (13.2±3.2) compared with WTbmf+/+ (7.3±1.5), not rescued by deletion of bmf (DNHNF-1αbmf−/−P=1.0, WTbmf−/−P=0.7)." (PMID 27551471, 2015).
Insulin resistance (continued). "All these data not only indicate that the diminished beta cell amount in GK rats is sufficient to supply insulin, even if at diminished levels in some individual animals, but also reflect that the completely developed insulin resistance in GK rats prolongs the half-time of blood circulating insulin." (PMID 26236746, 2015). "Berberine mimics insulin action and attenuates insulin resistance by increasing IR phosphorylation." (PMID 26783411, 2015). "Insulin induces cardiac and renal hypertrophy and remodeling during insulin resistance and hyperinsulinemia in type 2 diabetes by NF-κB activation, which may further contribute to development of hypertension." (PMID 26055622, 2015). "Finally, we should rather have evaluated insulin resistance by measuring plasma insulin concentration instead of HbA1c in our relatively healthy participants." (PMID 25880734, 2015). "Acutely, CHP may help glucose metabolism by enhancing glucose-induced insulin secretion, a benefit to those with insulin resistance." (PMID 26703752, 2015). "Insulin resistance plays an important role in hepatic steatosis, and the improvement of insulin sensitivity may be one of the mechanisms of DHA/EPA in correction of hepatic steatosis in SKO mice." (PMID 26690553, 2015). "Studies indicating that IL–6 is associated with insulin resistance are challenged by several findings showing that IL–6 actually has insulin-sensitizing effects and that blocking of IL–6 may induce insulin resistance." (PMID 26448147, 2015). "Since hyperglycaemia stimulates insulin secretion, chronic hyperglycaemia could also serve to increase insulin resistance, by the over-production of insulin." (PMID 25774201, 2015). "Impaired insulin biosynthesis and secretion are known to lead to further insulin resistance 2,3." (PMID 25726699, 2015). "Based on our findings, selected patients with insulin resistance, i.e. overweight patients, may nonetheless benefit from steroid-free maintenance immunosuppression, since corticosteroids negatively affect insulin sensitivity." (PMID 26398489, 2015). "For women attending the university hospital, indices of insulin sensitivity such as the reciprocal of the homeostasis model assessment of insulin resistance (1/HOMA-IR) and an index of beta-cell function, the Insulin Secretion-Sensitivity Index-2 (ISSI-2) were calculated." (PMID 26497130, 2015). "In immediate relatives of individuals with T2DM, insulin resistance has been shown to already exist when the glucose levels are normal, and dysfunction in insulin secretion has been found to be a key factor in determining the progression of glucose intolerance." (PMID 25574243, 2015). "Exploration of the effects of T2D-associated variants on glucose and insulin traits in non-diabetic populations has shown that most of the known loci act through an effect on insulin secretion rather than insulin resistance." (PMID 25774817, 2015). "Furthermore, we have shown an impact of this polymorphism on the fasting lipid profile, insulin and HOMA-IR, a surrogate measure of insulin resistance." (PMID 25793007, 2015). "Moreover, we observed that this process is associated with improved insulin resistance possibly owing to decreased FFA flux, as ATGL has been linked with increased insulin sensitivity and increased plasma FFA mobilization." (PMID 26663986, 2015). "This could be explained by the role of insulin resistance and elevated insulin level in RAGE −/− mice leading to change in energy expenditure which caused the weight gain in these animals." (PMID 26690206, 2015). "When stratified by the degree of intrahepatic fat, subjects with greater quantities of liver fat had increased alanine aminotransferase (ALT) (p < 0.001), visceral fat (p = 0.053), insulin (p = 0.008), and insulin resistance (indicated by HOMA-IR and adipo-IR, p = 0.019 and p = 0.002, respectively)." (PMID 25925168, 2015).
Insulin resistance (continued). "Additionally, we examined the effect of resveratrol on insulin resistance index, serum glucose and serum insulin levels." (PMID 25999625, 2015). "Moreover, these disorders share a common pathological condition, insulin resistance, which entails a progressive reduction in the responsiveness of peripheral tissue to insulin due to nutritional overload, chronic inflammation, dyslipidemia, and hyperglycemia." (PMID 26023930, 2015). "Furthermore, NAADP signaling has been implicated in the action of peroxisome proliferator-activated receptor γ agonists in their insulin-sensitizing actions to ameliorate insulin resistance." (PMID 26152717, 2015). "Chronically elevated insulin levels can reduce IR expression in the liver and primary adipocytes and in the kidney, and it is a possible mechanism that exasperates development of insulin resistance." (PMID 26257839, 2015). "It was obvious that our model of T2DM exhibited elevated insulin level which could be a result of insulin resistance in peripheral tissues." (PMID 25838947, 2015). "However, men with fatty liver were insulin resistant after an overnight fast because they had higher insulin levels, which was confirmed by an index of hepatic insulin resistance (ie, EGP × FPI) and HOMA-IR." (PMID 25250633, 2015). "Interestingly, there is a paradoxical expression of insulin resistance in PCOs, whereby insulin-stimulated androgen production persists while its role in glucose metabolism is impaired." (PMID 25866568, 2015). "Insulin resistance may be involved in insulin-dependent and insulin-independent signal transduction pathways in unloaded soleus muscle." (PMID 25713812, 2015). "Recently, studies in male albino Wistar rats suggested that DEHP induces insulin resistance in adipose tissue via increased reactive oxygen species production and lipid peroxidation that disrupts insulin signaling in adipose tissue and favors glucose intolerance." (PMID 26630026, 2015). "In any case, PASK inhibits glucagon secretion and decreases the blood glucose level; therefore, it is theoretically possible to treat such metabolic diseases as insulin resistance, inadequate insulin secretion, and type II diabetes by effectively regulating glucagon and insulin secretion." (PMID 26371032, 2015). "Glucose tolerance and insulin sensitivity were significantly improved in HF-fed CD47-/- mice as compared to HF-fed WT mice, suggesting that CD47 deficiency protects mice from diet-induced glucose intolerance and insulin resistance." (PMID 25747123, 2015). "Since oxidative stress is one of the main inducers of insulin resistance, it is conceivable that Nrf2 may play a regulatory role in insulin signaling pathway." (PMID 25909991, 2015). "Furthermore, intramyocellular lipid accumulation activates Ser/Thr-kinase cascades, enhancing insulin resistance through impairment of both insulin stimulated glucose uptake and oxidation." (PMID 26649034, 2015). "In addition, rs831571 showed significant associations with the homeostatic model assessment of insulin resistance (HOMA-IR) and fasting insulin level after 48 weeks of treatment with repaglinide (P = 0.0235 and 0.0212, respectively )." (PMID 26024304, 2015). "Similarly, MnTBAP, a mitochondria-penetrating SOD mimetic, rescued GLUT4-myc cells from Ang II-induced insulin resistance confirming that scavenging mitochondrial O2• improved insulin sensitivity." (PMID 25993470, 2015). "Insulin resistance and BMI rather than glycemic abnormalities before surgery were associated with a longer duration of the postoperative insulin infusion (p = 0.004, p = 0.048)." (PMID 26322019, 2015). "Brown or “beige” fat expansion can enhance thermogenesis, lipid oxidation, insulin sensitivity, and glucose tolerance; conversely expanded visceral fat (VAT) is associated with insulin resistance, low-grade inflammation, dyslipidemia, and cardio metabolic risk." (PMID 26834634, 2015).
Insulin resistance (continued). "Furthermore, naringenin administration decreased plasma glucose levels in STZ-induced diabetic rats, improved insulin sensitivity in fructose-fed insulin resistant rats, and reduced insulin resistance in HFD mice." (PMID 26705405, 2015). "Another possible factor contributing to insulin resistance is the direct glycation of insulin." (PMID 25786107, 2015). "However, another study in primates using variable foraging demand as a model of ELS demonstrated that offspring that went on to consume chow had developed insulin resistance at 4 months of age, as measured by insulin clamps." (PMID 26441828, 2015). "Obesity is closely related to insulin resistance and type 2 diabetes because adipose tissue, which secretes various adipokines with autocrine and paracrine action, is central to the control of energy storage and whole body insulin sensitivity." (PMID 26633898, 2015). "Fasting insulin, insulin resistance, and lipids were evaluated." (PMID 26347891, 2015). "Everolimus may also be effective in refractory hypoglycaemia by interrupting the insulin-signalling cascade and inducing peripheral insulin resistance." (PMID 25755880, 2015). "Type 2 diabetes is induced when insulin secretion cannot compensate for insulin resistance." (PMID 25755673, 2015). "Moreover, the homeostasis model assessment of insulin resistance and the insulin sensitivity index was generally lower and higher, respectively, for fish oil group than other groups." (PMID 25671565, 2015). "However, CKD results in interference with the intracellular signaling pathway initiated by insulin, which results in insulin resistance." (PMID 26716684, 2015). "The relationship between measured variables and insulin resistance was evaluated using lasso logistic regression to identify statistical models that could accurately distinguish insulin-resistant animals." (PMID 26063458, 2015). "Our findings suggest that the decreased ability of pregnant women with GDM to compensate for oxidative stress was manifested as increased insulin resistance, reduced insulin sensitivity, and β-cell dysfunction, all of which may play important roles in GDM." (PMID 25915047, 2015). "First, estimation of insulin resistance based on HOMA-IR in diabetic patients may be distorted due to taking exogenous insulin with consequent development of pseudohyperinsulinemia." (PMID 27734010, 2015). "Dysregulation of insulin signaling may lead to several debilitating disorders such as insulin resistance, metabolic syndrome, type 2 diabetes (T2D), cardiovascular disease, and/or cancer." (PMID 26465754, 2015). "Furthermore, the results of the insulin tolerance test show that the HFD mice developed insulin resistance." (PMID 25950605, 2015). "Alternatively, since insulin signaling has been reported to decrease hepcidin release, lower serum hepcidin in individuals with high PWV may reflect more severe insulin resistance in this high-risk group." (PMID 26244503, 2015). "In fact, even within the control population PPP2R5C expression correlates with reduced insulin sensitivity, raising the hypothesis for future studies that increased PPP2R5C expression might play a causative role in insulin resistance." (PMID 26440364, 2015). "The interaction between inflammation and insulin resistance may explain the fact that insulin is required more often for the treatment of T2D patients with psoriasis requiring insulin more often." (PMID 26357664, 2015). "The first lipoprotein biomarker model (model 1) predicts insulin resistance in preimpaired animals with 88% accuracy 2 years prior to diagnosis when animals were still insulin sensitive and included total HDL and IDL lipoproteins, in addition to large HDL particles and HDL cholesterol." (PMID 26063458, 2015). "The generation of acetaldehyde may contribute to alcohol-induced insulin resistance in cardiac muscle as overexpression of ALDH2 in heart prevents some of the defects in insulin signal transduction and contractile function." (PMID 26426068, 2015).